DENND2B (DENN domain containing 2B)
Description:
[Isoform 1]: May be involved in cytoskeletal organization and tumorogenicity. Seems to be involved in a signaling transduction pathway leading to activation of MAPK1/ERK2. Plays a role in EGFR trafficking from recycling endosomes back to the cell membrane. [Isoform 2]: Guanine nucleotide exchange factor (GEF) which may activate RAB9A and RAB9B. Promotes the exchange of GDP to GTP, converting inactive GDP-bound Rab proteins into their active GTP-bound form. [Isoform 3]: May block ERK2 activation stimulated by ABL1 (Probable). May alter cell morphology and cell growth (Probable).
Synonyms: HTS1; ST5; p126
Tractability: Antibody: UniProt places it where antibodies can reach, with high confidence; its Gene Ontology location is reachable by antibodies, with medium confidence. PROTAC: ubiquitination databases record sites on it.
Gene: Protein-coding gene on chromosome 11 (8,693,343 to 8,910,951, reverse strand). Ensembl gene ENSG00000166444.
Subcellular location: Cytoplasm, cell cortex (Isoform 1); Cell membrane; Recycling endosome
Subcellular location (Human Protein Atlas): Nucleoplasm
Pathways (Reactome):
Vesicle-mediated transport: RAB GEFs exchange GTP for GDP on RABs
Gene Ontology:
Molecular function: guanyl-nucleotide exchange factor activity; protein binding
Cellular component: plasma membrane; recycling endosome; cell cortex
Genetic constraint (gnomAD): Loss-of-function variants: 32 observed, 115.32 expected, observed/expected ratio (o/e) 0.28, 90% interval 0.21 to 0.37. The upper end of that interval is the gene's LOEUF score, 0.37, which puts it in group 1 of 6, group 1 being the genes least tolerant of losing a copy. Missense variants: 1,275 observed, 1,523.4 expected, observed/expected ratio (o/e) 0.84, 90% interval 0.8 to 0.88. Synonymous variants: 586 observed, 601.15 expected, observed/expected ratio (o/e) 0.97, 90% interval 0.91 to 1.04.
Homologues: Orthologues: chimpanzee DENND2B (99% identical), macaque DENND2B (96% identical), rabbit DENND2B (95% identical), dog DENND2B (95% identical), guinea pig DENND2B (94% identical), mouse Dennd2b (93% identical), rat Dennd2b (93% identical), pig DENND2B (88% identical), zebrafish dennd2b (65% identical), tropical clawed frog dennd2b (61% identical). Paralogues in human: DENND2A (43% identical), DENND2C (37% identical), DENND2D (19% identical).
Diseases named in the same sentence as DENND2B in open-access papers:
DENND2B is named in the same sentence as 25 diseases in open-access papers, as found by Europe PMC text mining. Sharing a sentence is not in itself a finding about the gene and the disease. The quoted sentences say what the papers report.
atherosclerosis (2 papers, 2022 to 2023). A disease characterized by the build-up of fatty material and calcium deposition in the arterial wall resulting in partial or complete occlusion of the arterial lumen. "Our study suggests that rare variation in genes including AMPD3, MICAL2, DPP6, and DENND2B may play a role in subclinical atherosclerosis, thereby making them promising novel candidates for the development of anti-atherosclerotic therapies." (PMID 35020748, 2022).
cancer (7 papers, 2015 to 2024). A tumor composed of atypical neoplastic, often pleomorphic cells that invade other tissues. "A multi-domain adaptor protein intersectin-s can integrate DENND2B (ST5) to promote the recycling of ligand-free epidermal growth factor receptor (EGFR) to the cell surface that is a reoccurring theme in cancer cell growth." (PMID 34395234, 2021).
infection (4 papers, 2008 to 2024). The state of being infected such as from the introduction of a foreign agent such as serum, vaccine, antigenic substance or organism. "Similarly, observed downregulation Rab9a GEF-encoding genes, DENND2a and DENND2b, in the E phase of infection does not correlate with the increase of Rab9a membrane-associated pool within the inner PrAC." (PMID 33042998, 2020).
DENND2B also shares sentences with these, for which no sentence is quoted: tumor (4 papers); osteosarcoma (2); adenocarcinoma (1); breast carcinoma (1); breast tumor (1); Charcot-Marie-Tooth disease (1); Diarrhea (1); Fundus dystrophy (1); gastric cancer (1); Immunodeficiency (1); invasive breast carcinoma (1); lung adenocarcinoma (1); malaria (1); nemaline myopathy (1); nephronophthisis (1); nephrotic syndrome (1); non-syndromic intellectual disability (1); pancreatic cancer (1); rheumatoid arthritis (1); uterine cancer (1); Uterine leiomyoma (1); uterine tumour (1).